IL1B (interleukin 1 beta)
Diseases named in the same sentence as IL1B in open-access papers (continued):
Sharing a sentence is not in itself a finding about the gene and the disease.
Stroke (continued). "For time-to-event analysis, MPO-DNA, Caspase-1 and IL-1β at baseline were predictors of MVEs after stroke (HR:4.04 (95%CI 1.28-12.70), 2.33 (95%CI 1.06-5.12) and 4.09 (95%CI 1.39-11.99), respectively)." (PMID 39737165, 2024). "By contrast, neutralization of cfDNA after stroke by therapeutic administration of recombinant DNase following stroke induction again significantly reduced the plaque inflammasome activation, as measured by caspase-1 cleavage and IL-1β secretion." (PMID 39112714, 2024). "paper documents that giving IL-1β antibodies after stroke to mice, partially reduces changes in gene expression of innate immune cells." (PMID 39592575, 2024). "Exercise preconditioning inhibited the protein expression of NLRP3, Caspase-1, IL-18, and IL-1β to improve cognitive dysfunction in stroke mice." (PMID 38317957, 2024). "For detail, MPO-DNA, PAD4, C1q, IL-1β, IL-6 and IL-8 reached their peak at 24 hours after stroke onset and show a decreasing trend throughout the acute phase of stroke, while HMGB1 peaked at 48 hours after stroke onset." (PMID 39737165, 2024). "Our study also showed that CX3CR1 gene deletion inhibited the expression of NLRP3, ASC, caspase‐1, IL‐1β, IL‐18, and NF‐κB p65 protein after stroke." (PMID 38421089, 2024). "Experimental and clinical evidence indicates that targeting IL-1β is a promising therapeutic strategy in stroke patients." (PMID 37713268, 2024). "Our results suggest that future randomized controlled trials are warranted to evaluate the safety and efficacy of targeting NETs, AIM2, or IL-1β for improved stroke outcomes." (PMID 39737165, 2024). "Either transplantation of bone marrow (BM) from stroke mice or exposition to high levels of IL-1β was leading to similar cardiac dysfunction." (PMID 39592575, 2024). "Inflammatory mediators produced by microglia, such as pro-inflammatory cytokines (TNF-α, IL-1β, and IL-6), significantly promote neuroinflammation, thereby mediating stroke." (PMID 38468280, 2024). "Brain ischemic injury caused by stroke leads to systemic inflammatory responses and the production of various inflammatory mediators such as TNF‐α, IL‐6, and IL‐1β, which are also involved in the neuroinflammatory mechanisms of PSD." (PMID 38376033, 2024). "Various triggers, such as febrile seizures, stroke, infection, or trauma, can initiate an inflammatory cascade that releases pro‐inflammatory cytokines, such as IL‐1β and TNF‐α, and danger signals, such as HMGB1." (PMID 38361811, 2024). "The present results show that HGS stroke patients have significantly higher circulating levels of IL-1β, whereas IL-6 levels only showed a trend to increase and TNF-α levels were unchanged." (PMID 36536168, 2024). "Inflammatory response was determined by detecting levels of cytokines (interleukin-2 [IL-2], IL-4, IL-5, IL-8, IL-6, IL-10, IL-12p70, IL-17, tumor necrosis factor-α [TNF-α], interferon-γ [IFN-γ], IFN-α, and IL-1β) within 14 days after stroke onset." (PMID 38902691, 2024). "For the first time, our findings revealed that circulating NETs, PAD4, C1q, IL-1β, IL-6 and IL-8 levels peaked at 24 hours after stroke onset, followed by a gradual decline." (PMID 39737165, 2024). "Microglial polarization is triggered by DAMPs and IFNγ stimulation, which activate the NF-kB and STAT1 pathways, similar to macrophages, resulting in the release of cytokines including IL-1β and TNF-α that cause neuronal death following stroke." (PMID 39062789, 2024). "Further analyses of the inflammatory milieu in atherosclerotic CCA plaques revealed a substantial increase in local IL-1β production after stroke, suggesting stroke-induced inflammasome activation within atherosclerotic plaques." (PMID 39112714, 2024). "Crucially, our research revealed that platelets obtained from stroke patients boost production of IL-1β by BV2 cells accompanied by upregulated levels of COX-2 and p-JNK in comparison with co-cultures with platelets from healthy donors." (PMID 39256999, 2024).
Stroke (continued). "One particular study in stroke survivors that identified increased circulating IL1-β levels correlated this finding with reduced function measured via Barthel Index scores." (PMID 38802847, 2024). "These HGS stroke-induced effects occur in an environment of enhanced circulating levels of IL-1β, which suggests a link between severe carotid narrowing, inflammation, and carotid artery endothelial dysfunction." (PMID 36536168, 2024). "The serum MPO-DNA, PAD4, C1q, IL-1β, IL-6 and IL-8 reach their peak at 24 hours after stroke onset and show a decreasing trend during acute phase." (PMID 39737165, 2024). "This study also found that IGF-1 treatment inhibited levels of inflammatory cytokines such as TNF-α, IL-1β, and IL-6 at 4 h after stroke, while only IL-6 and IL-13 continued to be inhibited at 24 h after stroke, as did chemokines GRO-KC and CCL2." (PMID 37638322, 2023). "In the hours following stroke, the pro-inflammatory response peaks at 6 h where both microglia and astrocytes are activated, producing cytokines such as interleukin 1 beta (IL-1β) and tumor necrosis factor alpha (TNF-α)." (PMID 36831312, 2023). "In the present study, there was increased activity of TNF-α, IL-6, and IL-1β in the MCAO-induced animal group indicating the brain injury during the stroke." (PMID 35838888, 2023). "The P2 × 7 receptor, mostly expressed in microglia, in turn, commences the specific release of interleukin-1β (IL-1β) in addition to cytokines and triggers the glutamate release in the nearby regions of stroke." (PMID 37631018, 2023). "Binding of post-stroke double-strand cfDNA to AIM2 leads to increased blood IL-1β concentrations, which results in apoptosis of circulating lymphocytes." (PMID 37212886, 2023). "We have previously shown that the release of cfDNA from dying tissue or activated neutrophils leads to a rapid systemic AIM2-mediated inflammasome activation and subsequent increased levels of circulating IL-1β after stroke." (PMID 37212886, 2023). "Early RIC remarkably ameliorated the notable elevation of IL‐18 and IL‐1β levels after stroke as detected by ELISA (p < 0.05)." (PMID 37580991, 2023). "We have previously demonstrated that AIM2 inflammasome activation by cfDNA release after stroke and burn injury leads to IL-1β release." (PMID 37212886, 2023). "A previous investigation, however, highlighted the potential synergistically effects of TNF-α and IL-1β, considering their corresponding alleles together, on the risk of PSD at 2 weeks post-stroke." (PMID 36911716, 2023). "A151 treatment resulted in reduced expression of cGAS, AIM2, IL-1β and IL-18 after experimental stroke and decreased infarct volume and improved neurological deficits after stroke." (PMID 37212886, 2023). "Neuroinflammation plays a crucial pathological role in subsequent brain damage after stroke, and IL-1β has been identified as a key cytokine in stroke." (PMID 37266151, 2023). "Neutralizing IL-1β by an intravenous anti-IL-1β antibody improves neurological outcome after stroke in animals." (PMID 37697393, 2023). "Valeric acid increased the concentrations of IL-17, IL-1β, and IL-6 in the blood of mice with experimental stroke." (PMID 37697393, 2023). "Inhibit stroke-induced inflammatory response by decreasing the number of Ly-6Chigh MMs subset and reducing expression of TNFα, IL-6, IL-1β and MCP-1." (PMID 37342335, 2023). "The M1 subtype can secrete pro-inflammatory factors, including TNF-α and IL-1β, aggravating neuroinflammation post-stroke." (PMID 37464832, 2023). "After stroke, the levels of inflammatory cytokines in patients with cognitive abnormalities are higher than those in patients with normal cognition, such as IL-1β, IL-6, IL-8, IL-10, and IL-12, leading to nerve damage and decreased cognitive function." (PMID 37397457, 2023). "On the other hand, IL-1β and IL-6 were increased in the blood and brain in stroke mice that received valeric acid or transplantation of old mouse feces." (PMID 37697393, 2023).
Stroke (continued). "MCAO induces accumulation of the pro-inflammatory cytokine IL-1β accompanied by elevated CS at the early and delayed stages of stroke." (PMID 35625876, 2022). "On days one and seven of stroke, the concentration of IL-1β, MMP-8, OPG and RANKL in the patients’ saliva was assessed using the Elisa technique." (PMID 35893412, 2022). "In fact, previous studies reported a similar attenuated phenotype for canonical NLRP3 activation (transcription dependent priming) in monocyte-derived macrophages obtained from stroke or AMI patients that was accompanied by decreased IL-1β release." (PMID 35558073, 2022). "Yet, few retrospective clinical studies have provided evidence that pro‐inflammatory mediators such as IL‐6 and IL‐1β remained elevated in circulation even 3 months after stroke onset." (PMID 35971650, 2022). "Immune cells release cytokines and chemokines (such as TNF-α, IL-1β, IL-17, and IL-23) that exacerbate inflammation and increase infarct size after stroke." (PMID 35432726, 2022). "Several pro‐inflammatory mediators such as TNF‐α, IL‐1β, and IL‐6 have been proposed as key drivers of secondary vascular events after stroke." (PMID 35971650, 2022). "When MSCs were added to monocytes from stroke patients, they decreased the levels of IL-1β, and increased the levels of IL-10 significantly more as compared to when they were added to monocytes from control patients." (PMID 36277912, 2022). "Of the pro-inflammatory mediators, TNF-α and IL-1β are considered to be the most hostile components in stroke brains, as well as blood-derived macrophages and resident microglia whose sources have been reported." (PMID 35968363, 2022). "ELISA of plasma revealed significantly higher levels of IL-1β (P = 0.001) and IL-6 (P = 0.001) at baseline in stroke patients who later died." (PMID 35726919, 2022). "We have demonstrated that WBV treatment reduced the expression of IL-1β in the brains of female rats after stroke." (PMID 36062148, 2022). "It had been found that interleukin-1β (IL-1β) was positively correlated with the PSF at 6 months after stroke." (PMID 35273991, 2022). "The exacerbated stroke outcomes in diabetic mice were accompanied by the upregulated expression of inflammatory factors (including IL-1β, TNF-α, IL-6, CCR2, and MCP-1) in the ischemic brain." (PMID 35784349, 2022). "A process that drives neuroinflammation in stroke, for example, a rise in caspase-1 cleavage and release of IL-1β, results from the activation of the NLRP3." (PMID 36138981, 2022). "The M1 phenotype is pro-inflammatory and secretes IL-6, tumor necrosis factor (TNF), and IL-1β, which contribute to brain injury after stroke." (PMID 36685518, 2022). "Minutes to hours after stroke, the acute phase of stroke leads to production of pro-inflammatory cytokines, particularly IL-1β and TNF-α, which propagate the neuroinflammatory response through activation of danger signals." (PMID 35631536, 2022). "Stroke induces an acute inflammatory response characterized by elevated levels of a series of cytokines such as IL-1β, IL-6, and TNF-α in the cerebrospinal fluid." (PMID 35467483, 2022). "It has been reported that compared to controls, IS patients have higher IL-6, IL-8, and TNFα protein in plasma and lower IL-6, IL-8, TNFα, IL-1α, and IL-1β mRNA in leukocytes within 72 h after stroke." (PMID 36547090, 2022). "The pro-inflammatory cytokines TNF-α and IL1-β were reduced in plasma from stroke animals, whereas anti-inflammatory IL-10 was elevated for 3,6′-DP." (PMID 35631536, 2022). "Strikingly, the transcription levels of multiple pro-inflammatory factors including TNF-α, IL-1β and IL-6 were significantly down-regulated and the anti-inflammatory factor IL-10 was significantly up-regulated in the stroke lesions of kaempferol-treated rats." (PMID 36293548, 2022).
Stroke (continued). "In contrast, MG6 was defined as the “neutrophil-like” subset, with upregulated expression of Cxcr2, S100a8, Il1b, and Mmp9, perhaps representing a stroke-specific state of microglia in the aged brain after stroke." (PMID 36052339, 2022). "Additional support for reduced levels of TNF-α, and IL-6, in addition to IL-1β, comes from studies of chronic metformin pre-treatment in a rodent model of adult stroke." (PMID 35705953, 2022). "A previous study confirmed that genetic deletion of IL-1α and IL-1β in mammals leads to a substantial reduction in damage after experimental stroke." (PMID 36685518, 2022). "As an important inflammasome-related proinflammatory factor, IL-1β is closely related to a variety of central nervous system diseases, including spinal cord contusion, stroke, traumatic brain injury, Alzheimer's disease, etc." (PMID 39262872, 2022). "Past studies have demonstrated the inhibition of TNF-α and IL-1β expression via modulation of DAPK1 signaling in stroke." (PMID 36016577, 2022). "Stroke triggered peripheral inflammatory responses, indicated by the elevated levels of circulating IL-1β and TNF-α, which were lowered by HSYA and NAC." (PMID 35453413, 2022). "Levels of IL1β are known to be increased in stroke and chronic cerebral hypoperfusion,44, –46 thus representing an inflammatory marker in cerebrovascular disease." (PMID 35102790, 2022). "Neuroinflammation, in particular, post-stroke levels of IL-1β have been demonstrated to be downregulated after TAK1 inhibition in different stroke models." (PMID 34628598, 2022). "Peripheral administration of an IL-1β receptor antagonist is protective in both transient and permanent middle cerebral artery occlusion models of stroke, and the IL-1β antibody, canakinumab, was shown to be protective in strokes in a clinical trial." (PMID 33918659, 2021). "Inflammatory cytokines such as interleukin (IL)-1β, E-selectin and vascular adhesion molecules are commonly measured in stroke studies, since they are known to impede recovery and correlate with an increased damage volume." (PMID 33461169, 2021). "PSD is the most common clinical complication and sequelae of stroke, studies have shown that the levels of IL-6, IL-1β, and Hcy in patients with PSD are significantly higher than those in the normal population." (PMID 34040550, 2021). "There is evidence that TNF-a and IL-1B levels in the brain increase many-fold (up to 40 or 60 times) during the first 24 h after inducing stroke." (PMID 34600570, 2021). "Microglial pyroptosis can promote the release of intracellular IL-1β and IL-18, contributing to proinflammatory responses after stroke." (PMID 34630845, 2021). "For example, in mouse ischemic stroke models, lymphocytes infiltrating into the whole stroke brain were complicated with inflammatory cytokines IL-1α, IL-1β, IFN-γ, TNF-α, and IL-6 at 2 weeks after stroke." (PMID 34421544, 2021). "Caspase-1 activity, IL-1β, TNF-α, and NLRP3 have been demonstrated to be associated with modulation of apoptosis after stroke, causing activation of caspase-dependent pathways of cell death." (PMID 34257822, 2021). "Stroke also induced noticeable increases in the pro-IL-1β and IL-1β, which were again dramatically suppressed by curcumin treatment." (PMID 34630845, 2021). "For instance, the effects of IL-1β released after stroke can be neutralized by administration of IL-1β receptor antagonist." (PMID 34572077, 2021). "The levels of inflammatory cytokines IL-1β, TNFα, and IL-6 in the blood of stroke patients and MCAO/R mice are increased." (PMID 34422821, 2021). "On the opposite, administration of recombinant IL-1β exacerbated post-stroke neuroinflammation and worsened tMCAO outcome." (PMID 33770265, 2021). "Microglia, as the resident immune cells in CNS, can be activated after stroke and initiate neuroinflammation by producing cytotoxic and inflammatory factors including IL-1β and TNF-α to thereby exacerbate brain damage." (PMID 34898370, 2021).
Stroke (continued). "The inflammatory response in stroke is considered an important pathological mechanism leading to cerebral ischemia, which mainly influences the reduction of interleukin 1 beta (IL-1beta) gene expression and damages hippocampal neurons." (PMID 34483881, 2021). "Pro-inflammatory cytokines are elevated in post-mortem tissue of stroke patients, such as interleukin (IL) 6, IL-1β, interferon (IFN) γ, tumor necrosis factor (TNF) α and IL-15." (PMID 34966269, 2021). "It has been established that both PSD and stroke involve an increase in pro-inflammatory cytokines, in particular IL-1β, IL-6, IFN-γ and TNF-α." (PMID 33919670, 2021). "Larger strokes have been shown to be associated with lower levels of TNF-α, IL-1β, P-selectin, and ICAM-1 as compared to lacunar strokes." (PMID 35008440, 2021). "Conclusively, we showed that the receptors of NLRP3, NLRC4, and AIM2, the executors of Caspase-1 and−11 were the main contributors of-post stroke inflammasome activation, which participated in the production of IL-1β, IL-18, and GSDMD." (PMID 33967935, 2021). "In animal models of stroke, high NLRP3-inflammasome assembly and IL-1β expression occur, while NLRP3 deficiency improves neurovascular damage." (PMID 34257822, 2021). "Conversely, systemic IL-1β administration was shown to worsen neutrophilia and increase infiltration of these cells into the brain in a rodent model of stroke." (PMID 33407641, 2021). "In a MCAO model of stroke, acute stress was shown to increase brain ischemic damage, the effect of stress being mediated at least partially by pro-inflammatory cytokines IL1β and TNFα." (PMID 34948340, 2021). "Generally, elevated levels of circulating proinflammatory cytokines, including tumour necrosis factor-alpha (TNF-α), IL-6, and interleukin 1β (IL-1β), are related to a poor prognosis in stroke sufferers." (PMID 34335867, 2021). "These experimental studies are further corroborated by VaD and post-stroke patient studies, which both show increases in TNF-α, IL-1β and IL-6 within the CSF/serum that are associated with cognitive decline." (PMID 34884906, 2021). "We found that IL-1β and IL-6 levels were increased solely 24-h after stroke in Wistar rats (F = 3.351 *p < 0.05; F = 4.455 *p < 0.05 respectively)." (PMID 34408211, 2021). "The expression of both IL-1α and IL-1β was dramatically elevated in the ischemic hemisphere 6-24 hours after stroke onset." (PMID 34248961, 2021). "These mediators include proinflammatory cytokines such as interleukin 1 beta (IL-1β) and interleukin 6 (IL-6), which are released intracranially after a stroke and are responsible for local inflammation." (PMID 34393969, 2021). "The potential role of pro-inflammatory cytokines in brain damage from hypoperfusion is suggested by the observation of a cytokine storm after stroke and the efficacy of the IL-1β antibody, canakinumab, in stroke protection." (PMID 33918659, 2021). "mRNA expression of TNFα and IL-1β in ischemic brain tissue on day 3 after stroke onset was also decreased in mice treated with anti-DJ-1 antibody." (PMID 34014921, 2021). "Overall, it would be interesting to learn, what role plays SLURP-1 in the NLRP3 inflammasome induced release of IL1β as this was recently shown to be present in MC and to be attenuated by classical Chrna7 activation in a stroke model." (PMID 33815383, 2021). "IL-1β and TNFα levels in serum and plasma have been investigated and some studies reported an increase shortly after the stroke, whereas others did not." (PMID 34966269, 2021). "Elevated levels of IL-1β and IL-6 after cerebral ischemia are correlated with the stroke volume, severity and long-term outcome." (PMID 34408211, 2021). "The study has indicated that TNF-α, IL-1β, and IL-6 secreted by activated microglia involve in neuronal cell apoptosis at stroke onset." (PMID 34257822, 2021).